RRP9 (ribosomal RNA processing 9, U3 small nucleolar RNA binding protein)
Description:
Component of a nucleolar small nuclear ribonucleoprotein particle (snoRNP) thought to participate in the processing and modification of pre-ribosomal RNA (pre-rRNA). Part of the small subunit (SSU) processome, first precursor of the small eukaryotic ribosomal subunit. During the assembly of the SSU processome in the nucleolus, many ribosome biogenesis factors, an RNA chaperone and ribosomal proteins associate with the nascent pre-rRNA and work in concert to generate RNA folding, modifications, rearrangements and cleavage as well as targeted degradation of pre-ribosomal RNA by the RNA exosome.
Synonyms: U3-55K; RNU3IP2
Tractability: Small molecule: a structure with a bound ligand is known. PROTAC: UniProt records ubiquitination sites on it; ubiquitination databases record sites on it; its protein half-life has been measured.
Gene: Protein-coding gene on chromosome 3 (51,933,425 to 51,941,944, reverse strand). Ensembl gene ENSG00000114767.
Subcellular location: Nucleus, nucleolus
Subcellular location (Human Protein Atlas): Nucleoplasm
Pathways (Reactome):
Metabolism of RNA: Major pathway of rRNA processing in the nucleolus and cytosol; rRNA modification in the nucleus and cytosol
Gene Ontology:
Molecular function: protein binding; RNA binding; U3 snoRNA binding; snoRNA binding
Biological process: ribosomal small subunit biogenesis; rRNA processing; maturation of SSU-rRNA
Cellular component: box C/D methylation guide snoRNP complex; nucleolus; small-subunit processome; nucleoplasm
Genetic constraint (gnomAD): Loss-of-function variants: 35 observed, 66.23 expected, observed/expected ratio (o/e) 0.53, 90% interval 0.4 to 0.7. The upper end of that interval is the gene's LOEUF score, 0.7, which puts it in group 2 of 6, group 1 being the genes least tolerant of losing a copy. Missense variants: 533 observed, 645.13 expected, observed/expected ratio (o/e) 0.83, 90% interval 0.77 to 0.89. Synonymous variants: 254 observed, 249.95 expected, observed/expected ratio (o/e) 1.02, 90% interval 0.92 to 1.13.
Homologues: Orthologues: chimpanzee RRP9 (99% identical), macaque RRP9 (99% identical), dog RRP9 (95% identical), pig RRP9 (93% identical), rat Rrp9 (93% identical), mouse Rrp9 (93% identical), guinea pig RRP9 (92% identical), rabbit RRP9 (91% identical), zebrafish rrp9 (62% identical), tropical clawed frog rrp9 (61% identical), Drosophila melanogaster U3-55K (41% identical), Caenorhabditis elegans T02H6.1 (35% identical), and 1 more.
Diseases named in the same sentence as RRP9 in open-access papers:
RRP9 is named in the same sentence as 11 diseases in open-access papers, as found by Europe PMC text mining. Sharing a sentence is not in itself a finding about the gene and the disease. The quoted sentences say what the papers report.
colorectal cancer (3 papers, 2023 to 2024). A primary or metastatic malignant neoplasm that affects the colon or rectum. "In colorectal cancer, studies have found that high expression of RRP9 is associated with enhanced tumor proliferation and invasion capabilities, suggesting a potential role for RRP9 in the development of colorectal cancer." (PMID 37988222, 2023). "The higher the expression of RRP9 in colorectal cancer, the higher the RRP9, the worse the prognosis." (PMID 37988222, 2023). "Previously, elevated RRP9 expression has been reporter in colorectal cancer, and downregulation of RRP9 in colon cancer cells inhibits subcutaneous tumor formation in xenografted mice." (PMID 37591798, 2023). "The results of this study indicate that RRP9 and DDX21 are overexpressed in both colorectal cancer and keloids, and their high expression is associated with worsened prognosis." (PMID 37988222, 2023). "We used the SW620 colorectal cancer cell line, which carries wild-type RRP9, as a control." (PMID 38548901, 2024). "Furthermore, heightened RRP9 and Smurf1 expression correlates with the progression of human colorectal cancer." (PMID 37988222, 2023). "The polymerase chain reaction (PCR) results reveal that the core genes RRP9 and DDX21 are highly expressed in both colorectal cancer and scar tissue." (PMID 37988222, 2023). "We found that the core genes (RRP9 and DDX21) were highly expressed in colorectal cancer and scar tissue samples, while their expression was lower in normal samples." (PMID 37988222, 2023). "The Western blot (WB) results indicate that the core genes RRP9 and DDX21 are highly expressed in both early and late-stage colorectal cancer, with a more significant expression level observed in the late-stage." (PMID 37988222, 2023). "RRP9 and DDX21 exhibit high expression and significant roles in patients suffering from colorectal cancer and keloids." (PMID 37988222, 2023). "Heatmaps were generated to visualize the expression levels of core genes (RRP9 and DDX21) in the batch-corrected matrix of colorectal cancer and scar tissue datasets." (PMID 37988222, 2023). "Research suggests that RRP9 and DDX21 may play a role in the development of both colorectal cancer and keloids, but their exact molecular mechanisms and regulatory pathways have not been fully elucidated." (PMID 37988222, 2023). "RRP9 and DDX21's significant roles in colorectal cancer will be validated using public datasets." (PMID 37988222, 2023).
pancreatic cancer (2 papers, 2022 to 2023). "Further, RRP9 promotes gemcitabine resistance in pancreatic cancer through activating AKT signaling pathway." (PMID 37591798, 2023). "Thus, in addition to previously established methods of sensitizing pancreatic tumor cells to chemotherapeutic agents, RRP9 and its downstream effectors may be exploited as novel targets to increase PC chemosensitivity to gemcitabine." (PMID 36434608, 2022). "However, the role of RRP9 in pancreatic cancer drug resistance remains unknown." (PMID 36434608, 2022).
prostate carcinoma (2 papers, 2023). A carcinoma that arises from epithelial cells of the prostate gland. "Collectively, these results suggest that recovery from treatment‐induced downregulation of RRP9 is associated with treatment resistance, and that RRP9 protein is upregulated in metastases in prostate cancer." (PMID 37591798, 2023). "We found that the higher expression of GNL3, CHCHD8, PA2G4, and RRP9 genes with HR more than 1.0 was closely associated with poor overall survival and disease-free survival in prostate cancer patients." (PMID 37345060, 2023). "Further, increased RRP9 protein expression is associated with metastasis in prostate cancer." (PMID 37591798, 2023). "Based on the information CHCHD8, GNL3, PA2G4, and RRP9 genes were selected to further explore the prognostic significance in prostate cancer." (PMID 37345060, 2023). "Our analyzes further show that RRP9, a U3 small nucleolar protein essential for ribosome formation, undergoes changes at protein level during metastasis in prostate cancer." (PMID 37591798, 2023). "The GNL3, CHCHD8, PA2G4, and RRP9 genes were selected to predict their ability in overall and disease-free survival in prostate cancer patients." (PMID 37345060, 2023). "Collectively, these results suggest that RRP9 has tumor‐promoting functions in cancer, and that the utility of it in preventing prostate cancer metastasis should be explored." (PMID 37591798, 2023). "In our differential expression analysis, we found that CHCHD8, GNL3, PA2G4, and RRP9 have 27.0-, 38.6-, 12.8-, and 7.6-times higher expression in prostate cancer specimens in comparison to normal prostate tissue." (PMID 37345060, 2023). "Silencing of RRP9 induced apoptosis in prostate cancer cells, suggesting that RRP9 may support cancer cell survival." (PMID 37591798, 2023). "DDX6, NOL3, and RRP9 showed differential expression in RNA and protein data between primary cancer and CRPC, suggesting that these RBPs are regulated post‐transcriptionally in prostate cancer." (PMID 37591798, 2023).
acute myeloid leukemia (1 paper, 2025). Acute myeloid leukemia (AML) is a group of neoplasms arising from precursor cells committed to the myeloid cell-line differentiation. "Delving deeper into the mechanism, we identified RRP9—an essential gene for ribosome biogenesis and a key player in acute myeloid leukemia prognosis—as a critical component of the MYC pathway." (PMID 40781078, 2025). "Functional assays showed that overexpression of RRP9 promoted acute myeloid leukemia cell proliferation and resistance to the chidamide-cytarabine combination, whereas RRP9 knockdown impaired rRNA synthesis, reduced nucleolar size, and diminished protein production." (PMID 40781078, 2025).
colorectal tumors (1 paper, 2023). "CTD analysis revealed associations between the core genes (RRP9 and DDX21) and diseases such as proliferation, scar tissue, colorectal tumors, scleroderma, and inflammation." (PMID 37988222, 2023). "CTD analysis indicated that RRP9 and DDX21 are associated with proliferation, scar tissue, colorectal tumors, scleroderma, and inflammation." (PMID 37988222, 2023).
keloid (1 paper, 2023). An irregularly shaped, elevated mark on the skin caused by deposits of excessive amounts of collagen during wound healing. "Higher expression levels of RRP9 are associated with a more unfavorable impact on keloids." (PMID 37988222, 2023).
cancer (4 papers, 2023 to 2025). A tumor composed of atypical neoplastic, often pleomorphic cells that invade other tissues. "In the field of cancer research, abnormal expression of RRP9 has been associated with the occurrence and development of various cancers." (PMID 37988222, 2023).
tumor (4 papers, 2022 to 2024). "Treatment with a combination of the AKT inhibitor MK-2206 and gemcitabine significantly inhibited tumor proliferation induced by overexpression of RRP9 in vitro and in vivo." (PMID 36434608, 2022). "A subcutaneous xenograft tumor model was elucidated in BALB/c nude mice to examine the RRP9 role in PC in vivo." (PMID 36434608, 2022). "We found a significant increase in the tumor volume and weight, as well as luminescence, of RRP9-overexpressing cells after gemcitabine treatment compared to control cells." (PMID 36434608, 2022). "To determine whether RRP9 has a role in mediating gemcitabine sensitivity in PC cells in vivo, we established a subcutaneous xenograft tumor model." (PMID 36434608, 2022). "Similarly, IHC staining revealed elevated RRP9 expression in PC tissue compared to non-tumor tissue." (PMID 36434608, 2022). "Finally, we examined whether RRP9 promoted tumor growth and gemcitabine-induced chemoresistance through AKT signaling pathway in vivo using our mouse subcutaneous xenograft model." (PMID 36434608, 2022). "Using unsupervised clustering analysis, we found that many OS-known genes were differentially upregulated (Rrp9, Rcc1, Ran), while others were downregulated (Mylk, Nid2) in the BMT and tumor cells compared to the control BM cells." (PMID 38182577, 2024). "Treatment of RRP9-overexpressing PC cells with AKT inhibitor MK-2206 and gemcitabine significantly inhibited tumor proliferation." (PMID 36434608, 2022).
RRP9 also shares sentences with these, for which no sentence is quoted: breast carcinoma (1 paper); colon cancer (1); scleroderma (1).